CALML6 (calmodulin like 6)
Synonyms: CAGLP
Tractability: No criterion of Open Targets' tractability assessment is met for any kind of drug.
Gene: Protein-coding gene on chromosome 1 (1,915,108 to 1,917,296, forward strand). Ensembl gene ENSG00000169885.
Subcellular location: Cytoplasm; Nucleus
Subcellular location (Human Protein Atlas): Nuclear speckles; Centrosome; Cytosol; Nuclear bodies; Nucleoplasm; Vesicles
Gene Ontology:
Molecular function: protein binding; enzyme regulator activity; calcium ion binding
Biological process: microtubule cytoskeleton organization
Cellular component: cytosol; nuclear body; nuclear speck; nucleoplasm; cytoplasm; nucleus
Genetic constraint (gnomAD): Loss-of-function variants: 27 observed, 22.5 expected, observed/expected ratio (o/e) 1.2, 90% interval 0.88 to 1.65. The upper end of that interval is the gene's LOEUF score, 1.65, which puts it in group 6 of 6, group 1 being the genes least tolerant of losing a copy. Missense variants: 239 observed, 234.58 expected, observed/expected ratio (o/e) 1.02, 90% interval 0.92 to 1.13. Synonymous variants: 97 observed, 85.5 expected, observed/expected ratio (o/e) 1.13, 90% interval 0.96 to 1.34.
Homologues: Orthologues: chimpanzee CALML6 (98% identical), macaque CALML6 (98% identical), dog CALML6 (81% identical), Caenorhabditis elegans cal-1 (34% identical), Caenorhabditis elegans cal-3 (31% identical), Caenorhabditis elegans K03A1.4 (27% identical), Caenorhabditis elegans tnc-2 (27% identical), Caenorhabditis elegans pat-10 (25% identical), Drosophila melanogaster TpnC4 (25% identical), Caenorhabditis elegans B0563.7 (24% identical), Caenorhabditis elegans E02A10.3 (24% identical), Caenorhabditis elegans F35C12.3 (20% identical). Paralogues in human: CALM1 (38% identical), CALM2 (38% identical), CALM3 (38% identical), CALML3 (35% identical), CETN1 (31% identical), CABP4 (30% identical), CETN2 (30% identical), CABP5 (29% identical), CABP2 (29% identical), CETN3 (29% identical), CALML5 (28% identical), CABP1 (27% identical), and 8 more.
Diseases named in the same sentence as CALML6 in open-access papers:
CALML6 is named in the same sentence as 9 diseases in open-access papers, as found by Europe PMC text mining. Sharing a sentence is not in itself a finding about the gene and the disease. The quoted sentences say what the papers report.
breast carcinoma (2 papers, 2019 to 2023). "We found that CALM2 and CALML5 were significantly active in primary breast cancer, while CALML3 and CALML6 were significantly active in breast cancer liver metastasis." (PMID 31557971, 2019). "CALM2 and CALML5 were found to be significantly active in primary breast cancer, whereas CALML3 and CALML6 were significantly active in liver metastasis of breast cancer." (PMID 37958607, 2023).
glioma (1 paper, 2021). A benign or malignant brain and spinal cord tumor that arises from glial cells (astrocytes, oligodendrocytes, ependymal cells). "High expressions of CALD1, CALML4, CALML6, CALM1 and CALM2 were associated with IDH wildtype glioma." (PMID 34070840, 2021). "Results from both the TCGA and CGGA dataset suggest that the expression of CALD1, CALML4 and CALML6 was higher in WHO grade III glioma than WHO grade II glioma." (PMID 34070840, 2021). "However, in the CGGA dataset, only CALD1, CALML4 and CALML6 were associated with IDH wildtype glioma, and no specific relationship with CALM3, CALM1 and CALM2 expression was noticed." (PMID 34070840, 2021). "CALD1, CALML4 and CALML6 might serve as unfavorable biomarkers in glioma." (PMID 34070840, 2021).
Obesity (1 paper, 2019). Accumulation of substantial excess body fat. "Until now, the specific roles of ANO2, CAMK2D, SLC8A1, PDE2A, CALML3, GNG7, and CALML6 genes in olfactory-related dietary patterns and obesity in humans have not been apparently explored; therefore, further investigation in these research areas is warranted." (PMID 31057674, 2019).
oral cancer (1 paper, 2024). "Furthermore, compared to the normal cells HOK, the expression of CALML6 was higher in oral cancer cells, particularly in the high metastatic potential HSC-3 cell line, where it was most pronounced." (PMID 38745046, 2024).
tongue tumor (1 paper, 2024). "The protein expression level of CALML6 in tongue tumor tissue was higher than that in adjacent normal tongue tissue, as determined by immunohistochemistry." (PMID 38745046, 2024).
cancer (1 paper, 2024). A tumor composed of atypical neoplastic, often pleomorphic cells that invade other tissues. "Our study adds to this body of knowledge by not only confirming the mRNA transcription and protein expression of CALML6 in OSCC cells and normal oral cells but also by uncovering its novel role in regulating cancer cell migration." (PMID 38745046, 2024). "In summary, our study reaffirms the significance of CALML6 and the EP4/CALML6/CaMKK2/AMPK signaling pathway in OSCC progression, offering a comprehensive overview of their roles in cancer cell migration and suggesting them as potential targets for OSCC therapy." (PMID 38745046, 2024).
CALML6 also shares sentences with these, for which no sentence is quoted: Insulin resistance (1 paper); metastasis (1); oral squamous cell carcinoma (1).